SARM1 (sterile alpha and TIR motif containing 1)
Description:
NAD(+) hydrolase, which plays a key role in axonal degeneration following injury by regulating NAD(+) metabolism. Acts as a negative regulator of MYD88- and TRIF-dependent toll-like receptor signaling pathway by promoting Wallerian degeneration, an injury-induced form of programmed subcellular death which involves degeneration of an axon distal to the injury site. Wallerian degeneration is triggered by NAD(+) depletion: in response to injury, SARM1 is activated and catalyzes cleavage of NAD(+) into ADP-D-ribose (ADPR), cyclic ADPR (cADPR) and nicotinamide; NAD(+) cleavage promoting cytoskeletal degradation and axon destruction. Also able to hydrolyze NADP(+), but not other NAD(+)-related molecules. Can activate neuronal cell death in response to stress. Regulates dendritic arborization through the MAPK4-JNK pathway (By similarity). Involved in innate immune response: inhibits both TICAM1/TRIF- and MYD88-dependent activation of JUN/AP-1, TRIF-dependent activation of NF-kappa-B and IRF3, and the phosphorylation of MAPK14/p38. Acts as a non-self dsDNA sensor in a sequence-independent manner to elicit NAD(+) degradation and thus to promote programmed cell death.
Synonyms: hSARM1; MyD88-5; HsTIR; KIAA0524; SAMD2; SARM
Tractability: Small molecule: a structure with a bound ligand is known; a high-quality ligand is known. PROTAC: ubiquitination databases record sites on it; its protein half-life has been measured; a small molecule that binds it is known.
Target class: Enzyme; Hydrolase
Gene: Protein-coding gene on chromosome 17 (28,364,356 to 28,404,049, forward strand). Ensembl gene ENSG00000004139.
Subcellular location: Cytoplasm; Cell projection, axon; Cell projection, dendrite; Synapse; Mitochondrion
Subcellular location (Human Protein Atlas): Mitochondria
Pathways (Reactome):
Immune System: Activation of IRF3, IRF7 mediated by TBK1, IKKε (IKBKE); IKK complex recruitment mediated by RIP1; MyD88-independent TLR4 cascade; TRAF6-mediated induction of TAK1 complex within TLR4 complex; Toll Like Receptor 3 (TLR3) Cascade
Gene Ontology:
Molecular function: double-stranded DNA binding; NAD+ nucleosidase activity; NAD+ nucleosidase activity, cyclic ADP-ribose generating; NADP+ nucleosidase activity; protein binding; signaling adaptor activity
Biological process: NAD+ catabolic process; positive regulation of programmed cell death; response to axon injury; protein localization to mitochondrion; regulation of dendrite morphogenesis; modification of postsynaptic structure; negative regulation of MyD88-independent toll-like receptor signaling pathway; nervous system process; regulation of synapse pruning; signal transduction
Cellular component: cytoplasm; mitochondrion; cytosol; dendrite; microtubule; synapse; axon; cell surface; extrinsic component of synaptic membrane; glutamatergic synapse; microtubule cytoskeleton; mitochondrial outer membrane; neuromuscular junction
Genetic constraint (gnomAD): Loss-of-function variants: 60 observed, 52.64 expected, observed/expected ratio (o/e) 1.14, 90% interval 0.93 to 1.41. The upper end of that interval is the gene's LOEUF score, 1.41, which puts it in group 5 of 6, group 1 being the genes least tolerant of losing a copy. Missense variants: 913 observed, 860.1 expected, observed/expected ratio (o/e) 1.06, 90% interval 1 to 1.12. Synonymous variants: 417 observed, 370.69 expected, observed/expected ratio (o/e) 1.12, 90% interval 1.04 to 1.22.
Homologues: Orthologues: chimpanzee SARM1 (100% identical), macaque SARM1 (99% identical), dog SARM1 (96% identical), guinea pig SARM1 (94% identical), mouse Sarm1 (94% identical), rabbit SARM1 (93% identical), rat Sarm1 (93% identical), tropical clawed frog sarm1 (68% identical), zebrafish sarm1 (61% identical), Drosophila melanogaster Sarm (45% identical), Caenorhabditis elegans tir-1 (37% identical).
Diseases named in the same sentence as SARM1 in open-access papers:
SARM1 is named in the same sentence as 113 diseases in open-access papers, as found by Europe PMC text mining. Sharing a sentence is not in itself a finding about the gene and the disease. The quoted sentences say what the papers report.
neuropathy (26 papers, 2018 to 2026). A disorder affecting the nervous system that manifests with pain, tingling, numbness, and/or muscle weakness. "Collectively, our data establish NMNAT2 variants as the genetic basis of a human neuropathy and demonstrate an unexpected role for SARM1 as a driver of neuroinflammation in the peripheral nervous system." (PMID 36287209, 2022). "In a mouse model of a human motor neuropathy caused by loss of NMNAT2, SARM1 mediates a slowly progressive motor-predominant neuropathy with axon loss and muscle atrophy, both hallmarks of CMT2A." (PMID 36287202, 2022). "Sarm1 deletion has shown to have significant protective effects on axon loss in animal models of traumatic brain injury, metabolic neuropathy and several models of chemotherapy induced neuropathy." (PMID 37091921, 2023). "A larger sample size may support this association between SARM1 and clinical neuropathy scales." (PMID 38400192, 2024). "This suggests the potential therapeutic value of targeting both PS and SARM1 to treat diseases including SARM1-dependent neuropathies." (PMID 40496808, 2025). "Due to the crucial role of SARM1 in neuropathy, research and drug development efforts have been directed toward the creation of SARM1 inhibitors or intervening agents that target other alterations caused by SARM1." (PMID 41018229, 2025). "This provided an opportunity to subsequently isolate the role of Sarm1-dependent neuropathy in the onset and progression of diabetic skeletal disease (WT T1D with DPN versus Sarm1KO T1D without DPN)." (PMID 38175722, 2024). "In this study, we used mouse models of T1D and SARM1-dependent neuropathy to isolate the functional relationship between DPN and the onset and progression of diabetic skeletal disease." (PMID 38175722, 2024). "To define the parameters of generating SARM1-dependent neuropathy, we evaluated 331P1 in a model of CIPN, in which C57BL6 mice were administered a maximum-tolerated dose of PTX of 25 mpk twice." (PMID 39335636, 2024). "CDDP activates SARM1 and calpain leading to axon degeneration.SARM1 deficiency confers resistance to OXP-induced neuropathies in mice." (PMID 38275737, 2024). "We assessed the cross-sectional relationships between the SARM1 biomarker, clinical neuropathy scales, and nerve conduction parameters in 80 participants aged between 30 years and 60 years." (PMID 38400192, 2024). "SARM1 is a pro-neurodegenerative NADase, and Sarm1KO mice have been previously reported to resist the onset of neuropathy in settings of T1D and T2D." (PMID 38175722, 2024). "In conclusion, SARM1 showed a consistent correlation with clinical neuropathy scales and nerve conduction parameters after accounting for the influence of COVID-19 vaccination doses." (PMID 38400192, 2024). "SARM1 activation also occurs in additional conditions of high translational relevance, which include treatment with chemotherapy agents that induce neuropathy, and TNF-alpha triggered inflammation in an inflammatory model of glaucoma." (PMID 36090788, 2022). "Deletion of SARM1 prevented the development of neuropathy in the streptozotocin mouse model of type 1 DPN90." (PMID 36311537, 2022). "The SARM1 NADase enzyme is an attractive druggable target for intervening neuropathies and a variety of neurodegenerative diseases." (PMID 36090788, 2022). "Sterile α and Toll/IL-1 receptor motif–containing 1 (SARM1), the central executioner of axon degeneration, can induce neuropathy and is activated by dysfunctional mitochondria." (PMID 36287202, 2022). "Sarm1 has emerged as a therapeutic target to treat neuropathies derived from metabolic or chemical stress and physical injury of axons." (PMID 33688624, 2021). "Deletion of SARM1 has been shown to provide significant protection against axonal degeneration or loss in conditions such as traumatic brain injury (TBI) and chemometabolic neuropathy." (PMID 41018229, 2025).
neuropathy (continued). "In support, a SARM1-dependent increase in cADPR levels has been reported in sciatic nerves of 2-month-old mice harbouring the human NMNAT2 LOF mutations (Nmnat2V98M/R232Q), with SARM1 being required for the neuropathy phenotypes in these mice." (PMID 39352636, 2025). "Sarm1 inhibitors as a clinical management strategy for neuropathy and skeletal disease in T1D." (PMID 38175722, 2024). "This novel study aimed to visualize the serum SARM1 levels in humans and to confirm the hypothesis that serum SARM1 may be closely related to the severity of neuropathy in patients with T2DM as well as the possible effects of COVID-19 vaccination." (PMID 38400192, 2024). "Another challenge that lays ahead is to integrate the pathways identified through human disease cohorts into known signaling pathways mediating axon degeneration (for example, are processes disrupted by new neuropathy genes like SORD or COA7 upstream or downstream of Sarm1)?" (PMID 37614471, 2023). "SARM1 is emerging as a potential treatment target for multiple forms of neuropathy." (PMID 36311537, 2022). "However, in our sarmopathy model created using two hypomorphic Nmnat2 variants, we find that SARM1 is chronically activated leading to a slowly progressive neuropathy; thus, axon loss does not occur as an all-or-nothing event." (PMID 40496808, 2025). "In addition, this reveals that clinical SARM1 inhibitors, currently being developed for treatment of neuropathy, may also have benefits for diabetic bone through actions outside of the nervous system." (PMID 38175722, 2024). "In contrast, knockout of PARP1, CD38, SARM1, and DBC1 protects mice against neuropathy induced via a high fat diet (HFD) or chemotherapy-induced neuropathy." (PMID 38256175, 2024). "In contrast, the knockout of PARP1, CD38, SARM1, and DBC1 protect mice against HFD-induced neuropathy or chemotherapy-induced neuropathy." (PMID 35563288, 2022). "The activation of PARP1 or CD 38 also promotes axonal degeneration, whereas the knockout of PARP1, CD38, SARM1, and DBC1 protect mice against high fat diet (HFD)-induced neuropathy or chemotherapy-induced neuropathy." (PMID 35563288, 2022). "Global KO of Sarm1 prevents the onset of T1D bone disease in females, independent of neuropathy and the neural actions of SARM1." (PMID 38175722, 2024). "The participants who had received two doses of the COVID-19 vaccine showed a consistent positive (without reaching the statistical significance) between the SARM1 level and clinical neuropathy scales." (PMID 38400192, 2024). "This mirrors the permanent rescue and continued growth previously reported in Nmnat2 null axons in the absence of SARM1, suggesting complete efficacy in both toxic and inherited types of neuropathy." (PMID 34870595, 2021). "Our study demonstrated a consistent correlation between SARM1 and several clinical neuropathy scales, and despite that, it was not statistically significant with all the clinical scales, likely due to the small sample size; however, the correlations were consistently positive." (PMID 38400192, 2024). "We consistently observed a positive correlation (although only a few reached statistical significance) between SARM1 levels and clinical neuropathy scales, as well as a consistent negative correlation (with only one reaching statistical significance) between SARM1 and sensory nerve amplitudes." (PMID 38400192, 2024). "In this study we examined the role of several proteases and Sarm1 in CDDP-induced neurotoxicity and show that accumulation of DNA-platinum adducts in DRG neurons and distal axonal degeneration are dependent on calpain activation and development of neuropathy in mice requires Sarm1." (PMID 33318563, 2020). "SARM1 was correlated significantly (p < 0.05) with MNSIe and NSS in group A and showed a consistent positive correlation with the other neuropathy clinical scales in group A and group B without reaching statistical significance." (PMID 38400192, 2024).
neuropathy (continued). "Additionally, studies propose that it may not be NMNAT2 and SARM1 proteins that are crucial targets; instead, it is suggested that downstream players in different pathways significantly participate in axon degeneration and subsequent neuropathy development." (PMID 38275737, 2024). "However, our data remains consistent with the view that targeted knockdown or inhibition of SARM1 function is a promising strategy to ameliorate various neurological diseases, such as ALS or chemotherapy induced neuropathy, as this is unlikely to aberrantly affect PNS or CNS myelin in humans." (PMID 37091921, 2023).
amyotrophic lateral sclerosis (20 papers, 2017 to 2025). Amyotrophic lateral sclerosis (ALS) is a neurodegenerative disease characterized by progressive muscular paralysis reflecting degeneration of motor neurons in the primary motor cortex, corticospinal tracts, brainstem and spinal cord. "A potential prodegenerative role of chronic SARM1 activation has also been suggested in some cases of amyotrophic lateral sclerosis (ALS) featured by rare SARM1 variants that confer constitutive enzymatic activation." (PMID 37503611, 2023). "Finally, genetic variants of SARM1 that encode constitutively active enzymes are enriched in patients with amyotrophic lateral sclerosis (ALS) and other motor neuropathies." (PMID 36287202, 2022). "Genetic hyperactivation of SARM1 has also now been associated with amyotrophic lateral sclerosis." (PMID 34870595, 2021). "Similarly, SARM1 was associated with amyotrophic lateral sclerosis risk (p = 1.76 × 10−08) and has been previously reported to influence axonal degeneration." (PMID 32413284, 2020). "Therapeutically inhibiting SARM1 may therefore be a putatively viable strategy for treating neurodegenerative diseases characterized by axon loss, such as amyotrophic lateral sclerosis." (PMID 32413284, 2020). "Genome-wide association studies (GWAS) have associated SARM1 with amyotrophic lateral sclerosis (ALS), and gain-of-function mutations in SARM1 are notably prevalent in individuals affected by ALS and other motor neurone disorders." (PMID 40473123, 2025). "The function of SARM1 in regulating axon degeneration is conserved between humans, mice and zebrafish and the SARM1 locus has been identified in two Genome-wide association studies (GWAS) for Amyotrophic lateral sclerosis (ALS)." (PMID 37091921, 2023). "SARM1 inhibitors benefit from prior clinical development in other neurodegenerative contexts, with compounds advancing to phase I trials for amyotrophic lateral sclerosis (ALS)." (PMID 41237781, 2025). "In particular, SARM1 (p = 1.76 × 10−08 with amyotrophic lateral sclerosis) and CTSH (p = 5.57 × 10−05 with Alzheimer disease) represent the most promising candidates based on our evaluations." (PMID 32413284, 2020). "Notably, GWAS have flagged SARM1 variants in connection with amyotrophic lateral sclerosis (ALS), and increased activity of SARM1 has been reported in iPSC-derived neurons from Parkinson’s patients." (PMID 35163535, 2022). "For instance, the lead pQTL for SARM1, which had an effect on amyotrophic lateral sclerosis risk in the initial analysis (p = 1.76 × 10−08), did not provide evidence of an effect with any of the 700 outcomes assessed based on multiple testing corrections." (PMID 32413284, 2020). "We report seven rare missense or in-frame microdeletion human SARM1 variant alleles in patients with amyotrophic lateral sclerosis (ALS) or other motor nerve disorders that alter the SARM1 auto-inhibitory ARM domain and constitutively hyperactivate SARM1 NADase activity." (PMID 34796871, 2021). "Sarm1 deletion has been found previously to be protective against RGC death and axon degeneration in a neuroinflammatory model of glaucoma and in a mouse model of amyotrophic lateral sclerosis (ALS)." (PMID 35163535, 2022). "In addition, it has been reported that SARM1 gene knockout not only can prevent neuronal degeneration and perinatal death but also can inhibit toxic neuropathy, such as amyotrophic lateral sclerosis (ALS) and glaucoma-related degeneration." (PMID 36055989, 2022). "While loss of Sarm1 is broadly protective, this protection is not universal, as evidenced by failure of the Sarm1 knockout to protect against axon degeneration in a mouse model of amyotrophic lateral sclerosis." (PMID 33900577, 2021). "Sarm1 deletion was beneficial in the TDP-43Q331K model of amyotrophic lateral sclerosis-frontotemporal dementia, but had no significant impact on axonal loss or clinical course of mutant SOD1 model of amyotrophic lateral sclerosis." (PMID 32584865, 2020).